ENSG00000198211 (novel protein (MC1R-TUBB3 readthrough))
Gene: Protein-coding gene on chromosome 16 (89,919,165 to 89,936,092, forward strand). Ensembl gene ENSG00000198211.
Genetic constraint (gnomAD): Loss-of-function variants: 38 observed, 51.79 expected, observed/expected ratio (o/e) 0.73, 90% interval 0.56 to 0.96. The synonymous counts are far from expectation, so gnomAD's model fits this gene poorly and the ratio says little. Missense variants: 775 observed, 1,072.4 expected, observed/expected ratio (o/e) 0.72, 90% interval 0.68 to 0.77. Synonymous variants: 572 observed, 472.19 expected, observed/expected ratio (o/e) 1.21, 90% interval 1.13 to 1.3.